STAT3 (signal transducer and activator of transcription 3)
Diseases named in the same sentence as STAT3 in open-access papers (continued):
Sharing a sentence is not in itself a finding about the gene and the disease.
breast cancer (continued). "CTEN enhances transcriptional activity of STAT3 for enhancing the invasion and metastasis of breast cancer cells." (PMID 29985912, 2018). "The objective of this meta-analysis was to evaluate STAT3 and phospho-STAT3 expression on the prognosis of breast cancer patients." (PMID 29560131, 2018). "Previous reports have shown that bufalin enhanced TRAIL-induced apoptosis in MCF-7 and MDA-MB-231 breast cancer cells by activating the extrinsic apoptotic pathway, the downregulation of Cbl and the inhibition of STAT3/Mcl-1." (PMID 30574018, 2018). "Collectively, this work demonstrates that breast cancer-derived exosomes are capable of inducing IL-6 secretion and a pro-survival phenotype in macrophages, partially via gp130/STAT3 signaling." (PMID 29867925, 2018). "Further investigation revealed that nuclear EGFR complexes with STAT3 in breast cancer cells induce the expression of specific genes, such as the inducible nitric oxide synthase (iNOS)." (PMID 29914167, 2018). "STAT3 is involved in human breast cancer, in which high STAT3 levels are correlated with a poorer survival." (PMID 30026553, 2018). "Different upstream gene expressions related to STAT3 signaling have different impacts on human breast cancer subtype." (PMID 29560131, 2018). "It has previously suggested that IL-6 stimulated the proliferation of breast cancer cells mainly through the activation of STAT3 and cell migration through the activation of the RAS/MEK/ERK and PI3K/AKT signaling pathways." (PMID 29707128, 2018). "Meanwhile, CXCL7 is a cytokine which in turn activate STAT3/NF‐κB signaling, leading to self‐renewal of breast cancer stem cells and a positive feedback loop was formed." (PMID 29356357, 2018). "IL-6R Ab and a specific STAT3 antagonist inhibited the growth and metastasis of IL-6+ mammary cancer in vivo and dramatically reduced the accumulation of e-MDSCs." (PMID 30083161, 2018). "In breast cancer, a number of upstream regulators can lead to STAT3 activation and the effects of phosphorylation of STAT3 are equally wide-ranging." (PMID 29875329, 2018). "Galiellalactone, a natural fungal metabolite isolated from the ascomycetes, and its derivatives 16 and 17 also interact with STAT3 in order to inhibit its DNA binding and are effective in prostatic and breast cancer cell models." (PMID 29921764, 2018). "On the other hand, the IL-6/JAK/STAT3 autocrine activation loop is a critical driver of cancer progression and metastasis in breast cancer." (PMID 30581487, 2018). "Conversely, in ER+ breast cancer where the activation of STAT3 is low, high STAT3 mRNA levels indicate a better RFS probability." (PMID 29588647, 2018). "Our results indicated that STAT3, STAT4, STAT5a, STAT5b, and STAT6 were significantly associated with favorable OS in breast cancer patients, especially for high pathological grade patients." (PMID 29326301, 2018). "As mentioned in the Introduction, several studies have demonstrated that constitutive activation of STAT-3 occurs in a wide variety of tumors, including breast cancer, and participates in multiple cellular processes as well as in tumorigenesis." (PMID 30373171, 2018). "Several cancer-related signaling pathways have been reported to be activated by TRIM14, such as AKT pathway in osteosarcoma, NF-κB pathway in TSCC, Wnt/β-catenin pathway in glioma and STAT3 in breast cancer." (PMID 30555277, 2018). "Activation of STAT3 results from the binding of cmvIL10 to the IL-10 receptor, and has been described in breast cancer, ovarian cancer with poor prognosis, and to increase the spread of glioma cancer stem cells in malignant glioma." (PMID 30081496, 2018). "Aberrant downstream effects of IL17RB include promotion of ERK-signalling in thyroid cancer cells, and activation of NFkB or STAT3 in breast cancer cells." (PMID 30680064, 2018). "Downregulation of STAT3 and STAT5a/b has been suggested as a mechanism for anti-proliferative effects of some anti-cancer agents in breast cancer cells." (PMID 30453988, 2018).
breast cancer (continued). "Upstream of Jak2 and STAT3, IL6 is also linked to breast cancer metastasis: IL6 expression was found to be higher at the invasive leading edge of human primary breast cancer cells." (PMID 30558204, 2018). "We have previously reviewed the role of STAT3 and the inflammation/acute phase response in involution and breast cancer." (PMID 29875329, 2018). "It is thus, apparently, a striking paradox that STAT3 regulates cell death during mammary gland involution, and yet promotes survival of breast cancer cells." (PMID 29875329, 2018). "Co-immunoprecipitation and glutathione S-transferase (GST) pull-down assays demonstrated that MEG2 directly interacts with STAT3 in vitro, and this interaction was confirmed in in vivo mouse brain tissue and human breast cancer cells." (PMID 30208623, 2018). "In this study, we confirmed the efficacy of target therapy against IL-6 signaling and STAT3 phosphorylation in the treatment of breast cancer." (PMID 30083161, 2018). "In agreement with sustained STAT3 activation observed in breast cancer, unchecked cell division, resistance to cell apoptosis, as well as tumor growth in mice result from IL-6/STAT3 activation in mammary CSCs." (PMID 30081496, 2018). "The Stat3 signaling pathway was recently reported to contribute to tumour progression and the survival of breast cancer-derived stem cells." (PMID 30297887, 2018). "STAT3 is a validated drug target for cancer therapy and thus it is not surprising that piperlongumine was found to be able to induce apoptosis at low doses (IC50 from 0.16 up to 5.1 μM) in multiple breast cancer cell lines having increased STAT3." (PMID 29618945, 2018). "The prognostic value of signal transducer and activator of transcription 3 (STAT3) and phospho-STAT3 in breast cancer remains controversial in heterogeneous." (PMID 29560131, 2018). "miR-519d directly targets STAT3 for downregulation, thus functioning as a tumour suppressor in breast cancer." (PMID 29875329, 2018). "For example, Bcl-xL, MCL1, and survivin are STAT3 target genes that are downregulated in breast cancer cell lines treated with the small molecule hydroxamic acid–based and benzoic acid–based STAT3 inhibitors." (PMID 29875329, 2018). "The STAT3 signaling pathway is also important in the regulation of breast cancer proliferation and apoptosis." (PMID 29713287, 2018). "Here, we show that breast cancer-derived exosomes alter the phenotype of macrophages through the interleukin-6 (IL-6) receptor beta (glycoprotein 130, gp130)-STAT3 signaling pathway." (PMID 29867925, 2018). "For example, in MDA-MB-231 breast cancer cells, STAT3 interacts with hypoxia-inducible factor 1 α (HIF1α) protein to activate HIF target genes, including vascular endothelial growth factor." (PMID 29875329, 2018). "For example, niclosamide increases radio-sensitizing effects through down-regulation of Wnt/β-catenin signaling in breast cancer, and the disruption of STAT3 activity in human lung cancer, respectively." (PMID 30189637, 2018). "Our in vitro and in vivo studies revealed that honokiol inhibits EMT of breast cancer cells by suppressing STAT3 signaling resulting in repression of ZEB1 expression and its recruitment on the E-cadherin promoter." (PMID 30134816, 2018). "Altogether, these observations highlight the crucial role of STAP-2 in BRK-mediated STAT3 activation and tumor cell growth and propose this molecule as a potential therapeutic target and prognostic factor for breast cancer patients." (PMID 29914167, 2018). "Studies which investigated the STAT3 or phospho-STAT3 expression of patients with breast cancer on the basis of patient survival data or survival curve were eligible." (PMID 29560131, 2018). "Notch4 thus promotes estrogen-independent, endocrine therapy resistant growth of breast cancer cell lines possibly through a Notch4/STAT3/EMT regulated axis." (PMID 30515368, 2018).
breast cancer (continued). "Here, we focus on the role of STAT3 in breast cancer progression, discussing the potential contrasting roles of STAT3 activation in the establishment of locally recurrent and distant metastatic disease." (PMID 30231553, 2018). "On the other hand, we will discuss in more detail the results from recent publications that highlighted a new and even more contradictory role of STAT3 during breast cancer progression, in local recurrences and distant metastases." (PMID 30231553, 2018). "miR-1181 inhibits stem cell-like phenotypes and suppresses STAT3 in human pancreatic cancer, whilst miR-7 indirectly inhibits STAT3 and thereby decreases the number of breast cancer stem cells." (PMID 29588647, 2018). "XZH-5 and analogues are other examples of small compounds designed to recognize the SH2 domain of STAT3 to inhibit its phosphorylation and subsequently induce cell death in hepatocellular carcinoma and breast cancer cells." (PMID 29921764, 2018). "STAT3 inhibition can even directly induce apoptosis in prostate cancer lines; while persistent activation of STAT3 signaling would confer resistance to apoptosis in human breast cancer cells." (PMID 28061440, 2017). "Stat3 activation is involved in proliferation of gastric cancer, colon cancer, glioblastoma, ovarian cancer, and breast cancer." (PMID 28085101, 2017). "MiR-519d suppresses trophoblast cell invasion and migration by downregulating MMP2, suppresses breast cancer by inhibiting STAT3 expression, and inhibits tumor metastasis and MMP2 expression in chondrosarcoma and osteosarcoma." (PMID 28146423, 2017). "MDSCs isolated from breast cancer tissue have Stat3-dependent upregulation of indole amine 2,3 dioxygenase (IDO), an enzyme responsible for the catabolism of tryptophan." (PMID 28193698, 2017). "STAT3 can be constitutively activated in breast cancer, maintains the tumor initiating cell (TIC) population, and upregulates multidrug resistance protein 1 (MDR1)." (PMID 29262529, 2017). "Phosphorylated Stat3 expression was higher in the mouse mammary tumors from PIK3CA‐H1047R mice in comparison with tumors from Her‐2/neu transgenic mice, as determined by IHC and western blot analysis." (PMID 28296140, 2017). "In contrast, MT/Shc2F/2F mammary tumours, which are impaired in STAT3 immunosuppressive signals, are exquisitely sensitive to PD1 immune checkpoint inhibition." (PMID 28276425, 2017). "Marotta and the colleagues reported that the JAK2/STAT3 signaling pathway was required for growth of CD44+CD24− stem cell-like breast cancer cells." (PMID 28591704, 2017). "We also reported that fad104 suppressed the invasion and metastasis of melanoma and breast cancer cells by inhibiting the signal transducer and activator of transcription 3 (STAT3) activity." (PMID 29180690, 2017). "Taken together, these results indicated that PMM-172 primarily suppressed STAT3 activation and viability in STAT3-depedent breast cancer cells." (PMID 28588262, 2017). "STAT3 levels have been reported to correlate with prognosis for many types of cancers, such as acute myeloid leukemia, breast cancer, and anaplastic astrocytomas, among others." (PMID 28032598, 2017). "Further, metformin has been found to reduce the risk of cancer in diabetic patients and combination treatment of metformin with small molecule STAT3 inhibitors has been proposed as a method of improving therapeutic efficacy in breast cancer." (PMID 28114390, 2017). "Histological assessment of the mammary glands injected with MT/ShcA+/+ breast cancer cells and their corresponding STAT1- or STAT3-deficient counterparts revealed the presence of microscopic lesions in ∼40% of the mammary glands at necropsy." (PMID 28276425, 2017). "Exposure to paclitaxel-derived supernatants (autocrine factors) for 4 days resulted in a significant increase in the expression of phosphorylated NF-κB, IκBα and STAT3 proteins in the same line of breast cancer cells." (PMID 28703802, 2017).
breast cancer (continued). "As indicated by data from Oncomine database, compared with normal controls, the expressions of FAK, Src, ERK1/2, Stat3 mRNA increased, while the expressions of PPARγ, C21orf34 and E-cadherin decreased in human melanoma cancer and breast cancer." (PMID 28108732, 2017). "Together, our findings highlight that hybrid compounds similar to 6b that are novel, direct STAT3 inhibitors with ROS production activity are worth further investigation as potential therapeutics for breast cancer or drug-resistant breast cancer." (PMID 28397855, 2017). "On the other hand, studies showed that STAT3 signaling is required for the growth of CD44+/CD24− stem cell-like breast cancer cells." (PMID 29228728, 2017). "γ-tocotrienol in combination with EGFR inhibitors (erlotinib or gefitinib) suppressed STAT3 and Akt signaling in murine mammary tumor cells." (PMID 28594363, 2017). "To evaluate the specificity of the compounds for STAT-dependent cancer cells, we performed viability assays on two pairs of cell lines of prostate and breast cancer origin, with different basal STAT3 activity and differential dependence on STAT3 activity." (PMID 28636670, 2017). "Similary, STAT3 inhibition using a JAK inhibitor increased doxorubicin sensitivity in human metastatic breast cancer cells." (PMID 28186993, 2017). "In this work, we evaluated the ability of nobiletin to inhibit tumor angiogenesis by regulating Src/FAK/STAT3 signaling through PXN in ER+ breast cancer cells." (PMID 28468300, 2017). "It was of interest that in the MDA-MB-231 breast cancer cells examined in this study, the myr-R9-LyP-1 peptide gave greater knockdown of Stat3 and c-Myc than myr-R9-iRGD." (PMID 28666009, 2017). "Taken together, this proves the efficacy of Syndecan-1 targeting in dampening the inflammatory signaling mediated by NFκB or STAT3 in the two cellular models of different breast cancer subtypes." (PMID 28270211, 2017). "There is also a strong association between nuclear STAT3 and EGFR expression in breast cancer samples and this EGFR/STAT3 relationship enhances tumorigenesis." (PMID 29262529, 2017). "Constitutive activation of STAT3 has been demonstrated in most human cancers including breast cancer, leukemia and lymphoma, multiple myeloma, and gastric cancer, and is associated with a poor prognosis in colorectal cancer, gastric cancer, and ovarian cancer." (PMID 27835873, 2017). "We identified genomic regions commonly as well as uniquely bound by STAT3 across the breast cancer cell lines." (PMID 28030809, 2017). "Previous reports showed that increased expression of Twist and reduced expression of CD24 contribute to EMT and to CSC self-renewal through activation of transcription 3 (STAT3)-dependent pathways in liver and breast cancers." (PMID 28418843, 2017). "Recently, abnormal SHP-1/p-STAT3 signaling pathway was identified in various human malignant tumors, including multiple myeloma, hepatocellular carcinoma, breast cancer and triple-negative breast cancer." (PMID 28594363, 2017). "Constitutively activated STAT3 has been described in many human breast cancer cell lines and in 40–50% of primary human breast tumors, making it an attractive target for the development of potential anti-cancer therapies." (PMID 28856117, 2017). "In contrast, STAT1 deficiency in STAT3Low mammary tumours (MT/Shc2F/2F) significantly accelerated their growth, suggesting that STAT1 selectively confers an immune surveillance response in mammary tumours with low STAT3 activity." (PMID 28276425, 2017). "Consistently, our present study confirmed SH003 inhibition of STAT3 phosphorylation in different breast cancer cells." (PMID 29179443, 2017).
breast cancer (continued). "STAT3 has been reported to play a pivotal role in maintenance of stem cell-like breast cancer cells, which have been shown to be related to tumor recurrence, metastasis and chemo-resistance." (PMID 28878571, 2017). "A crosstalk between LEDGF/p75 activation and the STAT3/IL6 inflammatory pathway, implicated in PCa, has also been identified in HaCaT skin cancer cells and in breast cancer cells." (PMID 28212536, 2017). "We also analyzed the mRNA level of FAK, Src, ERK1/2, PPARγ, C21orf34, Stat3 and E-cadherin in human breast cancer using Oncomine Cancer Microarray database." (PMID 28108732, 2017). "Fifty percent of primary breast cancers and breast cancer cell lines contain constitutive activation of STAT3 as indicated by its phosphorylation of a conserved tyrosine residue." (PMID 28607534, 2017). "QCT has been reported to antagonize STAT3 signaling in B-cell lymphoma and breast cancer cells and down-regulate IL-6/STAT3 signaling in lung cancer cells." (PMID 28217098, 2017). "Constitutive activation of STAT3 accelerates cell proliferation, migration and tumor formation in several tumors, such as breast cancer and colorectal cancer." (PMID 28514765, 2017). "In an investigation of primary breast carcinomas and normal tissues via immunohistochemical assay, nuclear STAT3 is significantly correlated with EGFR expression in breast cancers." (PMID 27861147, 2017). "Strikingly, HBXIP up-regulates TNFR1 expression, forming a positive feedback loop of TNFR1/NF-κB (and/or p38)/STAT3/HBXIP/TNFR1 in breast cancer." (PMID 28938560, 2017). "Strong evidence of a functional link between inflammation and breast cancer cell transformation has been shown to be mediated by the activation of NF-κB signalling, increased IL-6 and STAT3 phosphorylation by Iliopoulos and collegues." (PMID 28416734, 2017). "After determining a set of set of conditions that facilitated the formation of stable complexes of siRNA, binding peptide, and endosomal release peptide, we tested the ability of these complexes to knock down Stat3 in the human breast cancer lines MDA-MB-231." (PMID 28666009, 2017). "To characterize STAT3 binding patterns associated with TNBC, we performed, in replicate, Chromatin Immunoprecipitation followed by massively parallel sequencing (ChIP-seq) in five basal breast cancer cell lines with a STAT3-specific antibody." (PMID 28030809, 2017). "Others have also demonstrated that inhibition of STAT3 decreases the TIC population in breast cancer cells." (PMID 29262529, 2017). "Inhibitors targeting various components of the IL-6/JAK/STAT3 pathway have been effective in a number of preclinical models of breast cancer." (PMID 28607534, 2017). "These new STAT3 inhibitors are promising candidates for breast cancer therapy, due to their drug-like properties and potent bioactivities in vitro and in vivo." (PMID 28397855, 2017). "The results suggested that transcription factor STAT3 promotes proliferation and migration in breast cancer cells." (PMID 29029463, 2017). "The expression level of the RORC and STAT3 was significantly decreased in breast cancer tissues compared to control samples." (PMID 29299026, 2017). "Nobiletin inhibited tumor angiogenesis by regulating Src, FAK, and STAT3 signaling through PXN in ER+ breast cancer cells." (PMID 28468300, 2017). "Several cytokines, including interleukin-6 and oncostatin M, control fascin expression through the activation of the signal transducer and activator of transcription 3 (STAT3) signaling pathway in breast cancer cells." (PMID 29162880, 2017). "Upstream of Stat3, Il6 tended to be highly expressed and hepatocyte growth factor (Hgf) is significantly highly expressed in mammary tumors arising in PIK3CA‐H1047R in comparison with Her‐2 transgenic mice." (PMID 28296140, 2017). "Constitutive activation of Stat3 protein (tyrosine-phosphorylated Stat3) has been observed in numerous kinds of tumors, including breast cancer." (PMID 28801613, 2017).